IL10 (interleukin 10)
Diseases named in the same sentence as IL10 in open-access papers (continued):
Sharing a sentence is not in itself a finding about the gene and the disease.
pneumonia (continued). "The genes IL-1α, IL1B, IL6, TNF-α, IL10, IFN-γ, and NOX4 had significantly greater gene expression levels in pneumonia-affected calves compared to the CON group." (PMID 40711280, 2025). "This is consistent with previous studies reporting that various cytokines and chemokines, such as IL-6, IL-8, IL-10 and IP10, are elevated in patients with HIV and pneumonia." (PMID 38251391, 2024). "In this study, we analyzed the levels of serum IL‐6, IL‐8, IL‐10, IL‐1β, sIL‐2R and TNF‐α in children with pneumonia." (PMID 37142438, 2023). "In patients with pneumonia, the IL-6, IFN-γ, G-CSF, M-CSF, IL-1Ra, IL-2Ra, IL-10, HGF, MCP-1, and MCP-3 expression levels showed a strong positive correlation." (PMID 35382755, 2022). "After 2 and 4 months, a delayed-type hypersensitivity (DTH) response, the degree of pneumonia-affected lung tissue, CFU, T cell count, and cytokine expression (IL-2, IL-4, IL-10, and IFN-γ) were determined." (PMID 35562916, 2022). "Acute pneumonia increased the expression of TNF-α, IFN-γ, IL-6, IL-2 and IL-17 genes, and decreased the expression of Foxp3, IL-10, and TGFβ1 genes in lung tissue homogenate of mice." (PMID 35782123, 2022). "It has a therapeutic impact on pneumonia model rats by reducing B lymphocytes, CD8+ ratio, and elevated levels of IL-1α, IL-1β, IL-2, IL-10, TNF-α, IFN-α, IFN-γ, IgM, IgG, CD4+/CD8+, and NK cells." (PMID 36388945, 2022). "Elevated concentrations of both pro- and anti-inflammatory plasma cytokines were observed in the pneumonia group, including G-CSF, HGF, IL-1b, IL-1RA, IL-2, IL-2Ra, IL-6, IL-10, IL-18, IP-10, monocyte chemoattractant protein-3 (MCP-3), and TNF-α." (PMID 36119044, 2022). "Effect of RYNM on serum IL-10, NOS2, COX-1, IL-6, TNF-α and NF-κB levels in pneumonia model rats (mean ± S.D., n = 10)." (PMID 33678123, 2021). "Further, increases in IL-6, IL-8, IL-10, IL-15, TNF-α, and IFN-γ have been reported in severe pneumonia compared with mild pneumonia." (PMID 34692846, 2021). "Indeed, in pneumonia caused by Klebsiella pneumonia murine model, pro-inflammatory cytokines such as TNF-α, IL-1, and IL-17 are required for bacteria clearance from the lungs, whereas the anti-inflammatory cytokine IL-10 impairs host defense in this infection model." (PMID 29166668, 2017). "Furthermore, in the third day of antibiotics therapy, IL6:IL10 serum levels higher than 5.0 predict persistence of the symptoms and may help medical decision in adjusting the therapeutics for severe cases, and discharge mild pneumonia cases." (PMID 27905908, 2016). "ROC curves illustrate the accuracy of IL-6, LBP and IL-10 concentrations, and CRB-65 and CRB scores, in predicting a severe course of pneumonia." (PMID 22348735, 2012). "The levels of several pro- and anti-inflammatory cytokines (including IL-1β, IL-6, IL-10, IL-13, G-CSF and TNFα) were examined in BAL fluid 24 hours after the onset of pneumonia in both genotypes." (PMID 23145105, 2012). "The predictive power of IL-6, IL-10 and LBP for a severe course of pneumonia was lower than that of CRB-65." (PMID 22348735, 2012). "We have shown that CCL5 inhibition resulted in lower IFN-γ-secreting CD4+ T cells and significantly more PspA-specific IL-10-producing CD4+ T cells, which corresponded with the transition from pneumococcal carriage to lethal pneumonia." (PMID 20195541, 2010). "Additionally, intestinal gram-negative bacterial overgrowth secondary to vancomycin treatment, although associated with slightly higher plasma TNF-α and IL-10 concentrations shortly after induction of pneumonia, did neither influence host defense or lung pathology during P. aeruginosa pneumonia." (PMID 19710930, 2009). "In HAP patients with subsequent septic shock, IL-1β, IL-6, IL-8 and IL-10 were superior predictive markers than TNF-α, E-selectin and conventional laboratory values and scores at the time of pneumonia diagnosis." (PMID 16280065, 2005).
pneumonia (continued). "In addition, IL-2, IL-4, IL-6, IL-10, TNF-α, and IFN-γ levels were elevated by varying amounts depending on the type of pneumonia." (PMID 41011430, 2025). "Cytokine profiling in this study indicated that patients with severe pneumonia exhibited significantly higher serum IL-10 levels compared to those with non-severe disease (median: 467.45 pg/ml vs. 280 pg/ml, p = 0.032)." (PMID 41018059, 2025). "Both serum IL-10 and serum PCT were significantly elevated in children with severe pneumonia." (PMID 41018059, 2025). "Moreover, IgM-enriched immunoglobulins were shown to enhance the anti-inflammatory response by increasing IL-10 levels and reducing the TNF-alpha in the bronchoalveolar lavage fluid of pneumonia models." (PMID 37959352, 2023). "In contrast, the levels of IL-10 were not significantly different between patients with and without pneumonia or hypoxemia." (PMID 35237279, 2022). "Bronchial lavage IL-10 levels increased from in pneumonia patients but decreased in patients without pneumonia." (PMID 34207063, 2021). "Very interestingly, a significant increase in serum IL-10 levels was observed already on day 1 in patients who developed pneumonia in comparison to patients without infections or who developed only a local infection." (PMID 32106601, 2020). "Significantly higher plasma levels of IL-2, IL-7, IL-10, G-CSF, IP-10, MCP-1, MIP-1α, and TNFα were found in patients with severe pneumonia developing ARDS and requiring ICU admission and oxygen therapy compared to non-ICU patients showing pneumonia without ADRS." (PMID 33362782, 2020). "Lung IL-10 (an anti-inflammatory cytokine) and SCF (a growth factor required for survival, proliferation, and differentiation of HSCs) levels in the recipient lung homogenates were significantly increased in the pneumonia mice receiving d3 BM-MNCs." (PMID 32867826, 2020). "Thus, severe respiratory failure (SRF)-aggravated pneumonia caused by SARS-CoV-2 might involve the following: a unique immunosuppressive pathway aimed at IL-10 overproduction via the inhibition of HLA-DR activation on APCs; high IL-10 secretion by macrophages and DCs." (PMID 33424804, 2020). "There was a significant difference in IL-10 levels between the control and experimental groups, but these did not reflect the severity of pneumonia." (PMID 31387541, 2019). "Our study highlights a new opportunity for future drug development using SCFAs as an adjunct therapy to ameliorate non-resolving pneumonia by maintaining IL-10 expression and reducing expression of pro-inflammatory cytokines like TNF." (PMID 28074841, 2017). "The ratio between the median of IL-6 and IL-10 serum levels in patients with severe and non-severe pneumonia was respectively 22 and 5 at admission, but 9 and 5 on D3, and 3 and 2 on D8 of antibiotics therapy." (PMID 27905908, 2016). "The frequency of the IL-10 -819 T/T genotype was significantly higher in patients with postoperative pneumonia than in patients without pneumonia (p = 0.0323)." (PMID 24804995, 2014). "The frequency of the IL-10 -819 T/T genotype was significantly higher in patients with pneumonia than in those without pneumonia (p = 0.0323)." (PMID 24804995, 2014). "At the 'diagnosis of pneumonia', TNF-α, IL-1β, IL-6, IL-8, IL-10 and E-selectin were significantly increased in those patients who had subsequent septic shock, compared to patients with pneumonia without subsequent septic shock." (PMID 16280065, 2005). "Notably, significantly higher plasma levels of IL-2, IL-7, IL-10, G-CSF, IP-10, MCP-1, MIP-1α, and TNFα were found in patients with severe pneumonia developing ARDS and required ICU admission and oxygen therapy compared to non-ICU patients showing pneumonia without ADRS." (PMID 34639132, 2021).
pneumonia (continued). "Cardiolipin-induced SUMOylation inhibits IL-10 production by lung CD11b þLy6GintLy6CloF4/80 þ cells because of the recruitment of a repressive nuclear receptor corepressor (NCOR)/ histone deacetylase 3 (HDAC3) complex to the IL-10 promoter, ending in persistent inflammation during pneumonia." (PMID 33467433, 2021). "Serum IL-10 (p = 0.0001), IL-6 (p = 0.002), MIP-3α (p = 0.02) and CD40-L levels (p = 0.002) significantly increased from time point A to B (5–9 day of illness to 10–21 day of illness) in deceased individuals and in those who developed severe pneumonia, when compared to those who had mild illness." (PMID 33199778, 2020). "UC-MSC therapy increased animal survival in E. coli-induced pneumonia, increasing the survival from 60% (9/15) in vehicle-treated animals to 91% (11/12) with naïve UC-MSC therapy and 82% (9/11) in the animals treated with IL-10 UC-MSCs (p < 0.05 versus vehicle)." (PMID 31200579, 2019). "In comparison with the control group, animals that received blocking HMGB1 antibodies after 60 days of infection showed a significant increase of pulmonary bacilli burdens, lower expression of IFNγ, TNFα and IL17, high expression of IL-10, and higher but not significant pneumonia (39+/3% vs 32+/3%)." (PMID 26201072, 2015). "IL-10 inhibits the production of reactive oxygen and reactive nitrogen intermediates when monocyte and macrophages are activated by IFN-γ and therefore may be important in determining the outcome of pneumonia." (PMID 24565171, 2014). "At diagnosis, IL-10 levels were lower (3.68 vesus 1.99, P = 0.074), and IL-6 levels were higher (44.07 versus 19.98, P = 0.155) in children with severe pneumonia than in children with non-severe pneumonia; however, no statistical difference was observed between the two groups." (PMID 27905908, 2016). "High levels of IL-6 and IL-10 could be useful biomarkers to discriminate non-COVID-19 pneumonia from COVID-19 pneumonia, which is in line with other reports where the IL-6 and IL-10 ratio has been suggested as a useful biomarker to discriminate severe pneumonia cases at admission." (PMID 40508859, 2025). "Children with COVID-19 pneumonia showed higher levels of serum interleukin-6 (IL-6), interleukin-10 (IL-10), and tumor necrosis factors-α (TNF-α) than children without pneumonia." (PMID 37735372, 2023). "The results showed that the expression levels of IL-6, IFN-γ, IFN-α1, IP10, IL-10, HMGB1, and the HMGB1/sRAGE ratio were comparable between patients with or without pneumonia." (PMID 35875560, 2022). "Significantly higher plasma levels of IL-2, IL-7, IL-10, G-CSF, IP-10, MCP-1, MIP-1α, and TNFα were found in patients with severe pneumonia developing ARDS compared to non-ICU patients showing pneumonia without ADRS." (PMID 34578468, 2021). "Another study found higher concentrations of IL-10 and IL-5 in H1N1-infected patients with pneumonia compared to H1N1-infected patients without pneumonia." (PMID 26407163, 2015). "By comparing the hub genes with the top ten genes of pneumonia, we found 5 overlapping genes (IL-1B, IL-6, CXCL8, TNF, and IL-10), which might interpret on how the YPFG exerts a therapeutic effect in some types of pneumonia but not all types of pneumonia." (PMID 36285159, 2022). "Consequently, IL-10 is a negative feedback mechanism to suppress acute respiratory distress syndrome (ARDS), damage to vital organs, and severe pneumonia." (PMID 36679902, 2022).
liver fibrosis (169 papers, 2008 to 2025). "Plasma IL-10/IL-17A ratio was associated with the histological advancement of liver fibrosis (Kruskal-Wallis, p=0.028)." (PMID 40918132, 2025). "In a group of patients with advanced liver fibrosis, liver steatosis was linked with lower serum concentrations of IL-4, IL-5, IL-9, IL-10, IL-13 and IL-22." (PMID 39200991, 2024). "Bregs from patients with chronic hepatitis B or hepatitis B virus(HBV)-associated hepatic fibrosis can inhibit the function of Th1 and Th17 through intercellular contact and secretion of IL-10." (PMID 36875101, 2023). "Liver fibrosis in ruminants has previously been associated with expression of IL10 and TGFB, with an increased expression of these genes potentially leading to increased fibrosis and control of fluke burdens." (PMID 34616397, 2021). "IL-10 is known for its regulatory function, and some experimental studies show an association between its absence and accelerated liver fibrosis in schistosomiasis." (PMID 34970264, 2021). "Conversely, Siglec-F+CD11b+ eosinophils were reduced in the livers of IL-10-deficient mice with liver fibrosis." (PMID 34124102, 2021). "At thermoneutrality, with CCl4 administration, IL-10-deficient mice exhibited more severe liver fibrosis than wild-type mice." (PMID 34124102, 2021). "Reduction of hepatic neutrophils and macrophages as well as reduced liver fibrosis was accompanied by a reduction of gene expression levels associated with inflammation (Tnfα, Il10, and Tgfβ) and less pronounced fibrosis (Col1a1, Timp, and Ctgf)." (PMID 32316235, 2020). "IL-10 regulates anti-fibrotic processes, while low levels of IL-10 was associated with severe hepatic fibrosis during schistosomiasis patients." (PMID 32922381, 2020). "On the other hand, repression of STAT3 expression was found to exacerbate liver inflammation in interleukin-10-deficient mice and accelerate hepatic fibrosis during cholestasis." (PMID 29615085, 2018). "In the current study, low IL-10 levels were associated with moderate/severe hepatic fibrosis while IL-13 was raised in this group." (PMID 29610679, 2018). "Serum cytokine signature showed that mild liver fibrosis is associated with higher IL-10 serum levels as compared to severe liver disease." (PMID 26742960, 2016). "Egg-induced inflammation, large granulomas, hepatic fibrosis, and tissue eosinophilia were observed in IL-10/IL-12-deficient mice with schistosome infection." (PMID 26891172, 2016). "Given the possible association between TF production and liver fibrosis, this finding further supports a potential inverse relationship between IL-10 and liver fibrosis." (PMID 25884329, 2015). "Hepatic fibrosis was increased in IL-6−/− mice and in IL-10−/− mice due to the loss of hepatocyte protection." (PMID 22973518, 2012). "Importantly, we demonstrated that increased Tfr cell population and Breg-derived IL-10 secretion collectively contribute to the amelioration of schistosomiasis-associated hepatic fibrosis." (PMID 41154658, 2025). "Upregulated pathways in infected cells included elevated interleukin-10 signaling, pattern recognition receptor responses, growth factor signaling, and signaling associated with pathogenic processes (pulmonary fibrosis, hepatic fibrosis, osteoarthritis, cancer)." (PMID 39902963, 2025). "In animal models of hepatic fibrosis caused by long exposure to CCl4, IL-10 demonstrated anti-fibrotic effects, suggesting that IL-10 action is time-dependent and may involve a direct antifibrotic mechanism." (PMID 37894792, 2023). "In addition, IL-10 level is associated with several of its gene polymorphisms and is associated with liver fibrosis progression and cirrhosis susceptibility in HBV-infected patients." (PMID 36052277, 2022).
liver fibrosis (continued). "In humans, IL10 treatment normalizes serum ALT level, improves liver histology and reduces liver fibrosis in patients with chronic hepatitis C 53, and the high IL10 production haplotype of its gene promoter is associated with reduced susceptibility to liver cirrhosis." (PMID 33391480, 2021). "Additionally, as little as 50 mg/kg of HD is sufficient to alleviate liver fibrosis from several causes, including the inhibition of NF-κB/IL-1β/IL-10 and TGF-β/Smad2/3/CTGF signaling pathway and prevention of HSC activation." (PMID 32863858, 2020). "One possible reason for the therapeutic effects of DC-IL10 on liver fibrosis might be associated with their capacity to secrete high levels of IL-10 and directly reduce liver inflammation." (PMID 30800002, 2019). "This haplotype has been correlated with a decreased synthesis of IL-10, suggesting that a lower anti-inflammatory activity could be implicated in the progression of liver fibrosis." (PMID 23840511, 2013). "Thus, while IL-6 triggers proinflammatory responses in macrophages, IL-10 mediates anti-inflammatory responses that are associated with decreased liver fibrosis." (PMID 22973518, 2012). "But Th2 cytokines such as IL-4, IL-10 and IL-13 are associated with the aggravated pathological injuries and our previous study showed that the imbalanced Treg/Th17 may play a role in the formation of liver fibrosis." (PMID 28151995, 2017). "The plasma ratio of IL-10/IL-22 differentiates the degree of liver fibrosis (Kruskal-Wallis, p=0.03)." (PMID 40918132, 2025). "Elevated IL-10 expression in human liver tissues reduces hepatocyte apoptosis and reverses liver fibrosis." (PMID 39995661, 2025). "Previous studies in other models of liver inflammation have shown that IL-10 can reduce hepatic fibrosis, in part by limiting macrophage activation and altering T-cell function." (PMID 40643550, 2025). "IL-10 inhibits immune cell activation, attenuates hepatic inflammatory, and exerts protective effects on liver fibrosis progression." (PMID 39995661, 2025). "In a BDL-induced liver fibrosis model, Treg inhibition resulted in reduced IL-10 expression, increased fibrosis, and greater inflammatory cell infiltration." (PMID 39995661, 2025). "Specifically, 680 proteins in cluster 1, including pro- and anti-inflammatory cytokines (e.g., IL-6 and IL-10) and liver fibrosis markers (e.g., ACTA2, KRT19, and SPP1), increased progressively with fibrosis stages." (PMID 39889710, 2025). "During liver fibrosis, IL-10 mitigates fibrosis by suppressing inflammatory cellular immune responses and the production of TGF-β1, TNF-α, and tissue inhibitors of metalloproteinases." (PMID 39995661, 2025). "The IL-10/IL-17A ratio observed in our study, as well as the ratio of IL-10/IL-22, varied between various degrees of hepatic fibrosis (F0-F3)." (PMID 40918132, 2025). "During liver fibrosis, Polarized macrophages release anti-inflammatory factor IL-10, influencing fibrosis progression." (PMID 40248698, 2025). "Among these, the mRNA levels of nine genes, including USB1, NT5E, RORA, SDK1, and IL10, were significantly up-regulated, suggesting their involvement in the miRNA-30-mediated regulation of host hepatic fibrosis." (PMID 39139565, 2024). "A study demonstrated that IL-10 gene treatment attenuates liver fibrosis by inhibiting the activation and inducing the senescence of hepatic stellate cells and promoting the degeneration of collagen." (PMID 39596809, 2024). "The authors showed that the development of hepatic fibrosis was effectively inhibited by repeated intrahepatic injections of Ad-IL10 combined with CMCS." (PMID 39339355, 2024).